G3BP1 (G3BP stress granule assembly factor 1)
Diseases named in the same sentence as G3BP1 in open-access papers (continued):
Sharing a sentence is not in itself a finding about the gene and the disease.
cancer (83 papers, 2011 to 2026). A tumor composed of atypical neoplastic, often pleomorphic cells that invade other tissues. "Previous studies have reported that YBX1 and G3BP1 are associated with tumorigenesis, tumor progression, and resistance to chemotherapy in various types of cancer." (PMID 41513625, 2026). "G3BP1, a stress granule (SG) assembly factor, has been implicated in SG formation and cancer progression, making it a key protein of interest." (PMID 40346580, 2025). "We further uncovered a cancer-associated S33F CTNNB1 mutation which generates a novel binding site for G3BP1/2 (p + 3 position of the [FILV]xFG-motif)." (PMID 39009827, 2024). "Altered G3BP1 expression has been linked to cancer, neurodegeneration, and nerve injury, underscoring the importance of G3BP1 and stress granules in the control of cellular proteostasis under adverse conditions." (PMID 37442236, 2023). "To determine the functional roles of G3BP1 in cancer progression, we first performed a loss-of-function study by means of siRNA." (PMID 34967276, 2022). "More recently, the overexpression of G3BP-1 has been implicated in cancer, suggesting a functional role of G3BP-1 in tumorigenesis." (PMID 33500425, 2021). "Overexpression of G3BP1 has been implicated in a variety of human cancers, indicating the oncogenic function of G3BP1." (PMID 34707111, 2021). "Future studies will be required to dissect the potential role of MG53 in modulating the G3BP2/G3BP1 complex formation associated with SG signaling in cancer cells." (PMID 34521423, 2021). "Since the loss of G3BP1 is associated with age-related phenotypes, it is possible that G3BP1 modulates these effects by controlling cellular senescence and cancer growth." (PMID 33020468, 2020). "It was also suggested that G3BP1-associated signaling pathways are diverse in cancers, and more importantly, to be cancer type specific." (PMID 29717134, 2018). "Ras GTPase-activating protein SH3 domain-binding protein 1 (G3BP1), an essential Ras mediator, has been implicated in cancer development, including cell growth, motility, invasion and apoptosis." (PMID 25962958, 2015). "Are AEP and G3BP1 associated with cancer malignancy and prognosis?" (PMID 40858563, 2025). "Finally, according to the statistics of TCGA cohort, among all cancers, the mutation frequency of G3BP1 in EC is the highest, coming to 5.27% (27/512), including missense mutation, synonymous mutation, and nonsense mutation." (PMID 37904149, 2023). "However, it is important to mention that, in addition to its role in SGs, G3BP1 is also involved in various mechanisms that are linked to cancer and cell viability." (PMID 35713120, 2022). "G3BP1 has been implicated in several cancer-associated survival pathways including Ras." (PMID 23341773, 2013). "G3BP1, encoding the core components of stress granules, promoted DNA binding and activation of cGAS pathway, might unfold an unknown vision between microbe and cancer." (PMID 37917664, 2023). "To understand the impact of G3BP1 or G3BP2 on the RG7388-induced NOXA/Caspase-3 axis-mediated cancer cell death, we utilized siRNA technology to knock down G3BP1 and G3BP2, respectively." (PMID 40523886, 2025). "G3BP1-driven SG formation not only affects viral replication (35, –, 39, 46) but also plays roles in oncogenesis, cancer chemoresistance, and neurodegeneration occurrence." (PMID 40214262, 2025). "Cancerous tissues exhibited high levels of AEP and G3BP1 truncations, which were strongly associated with poor prognosis." (PMID 40858563, 2025). "The Western blot results revealed dose-dependent G3BP1 cleavage fragments in cancer cells after chemotherapeutic drug treatment." (PMID 40858563, 2025).
cancer (continued). "Our findings revealed that cancer cells had diffuse staining for G3BP1 in the membrane and cytoplasm, but nuclear staining was rarely observed." (PMID 38164170, 2024). "FXR1 is a constituent of stress granules, colocalizes with G3BP1, and has been reported to be overexpressed in cancer." (PMID 37196085, 2023). "Ras-GTPase-activating protein binding protein 1 (G3BP1) is an oncogenic factor, which highly expressed in a variety of cancers." (PMID 37904149, 2023). "Studies have shown that G3BP1 is a cancer-promoting factor that is highly expressed in a variety of tumors and is associated with tumor progression." (PMID 36330442, 2022). "CircEIF3H overexpression significantly promoted TNBC cell proliferation, Edu incorporation and colony formation in TNBC cells, and HSPD1/RBM8A/G3BP1 knockdown attenuated the cancer-promoting effect induced by the circEIF3H overexpression." (PMID 35568705, 2022). "In recent years, studies concentrating on the roles of G3BP1 in cancer have been gradually reported." (PMID 34967276, 2022). "Functional studies proved that G3BP1 promoted the malignant behaviors of cancer cells, including cell survival, metastasis, and the chemotherapy resistance of cancer cells." (PMID 35902727, 2022). "G3BP1, which can inhibit tumor cell apoptosis, is usually overexpressed in tumors and cancers, such as MCF-7 cells." (PMID 36552538, 2022). "Ras-GTPase-activating protein SH3 domain-binding protein 1 (G3BP1) is an SH3 domain-binding protein that has been reported to play a pro-cancer role in many types of cancer, including prostate cancer, breast cancer, and renal cell carcinoma." (PMID 35902727, 2022). "G3BP1 has been previously established to play a significant oncogenic role in the progression of cancers." (PMID 34967276, 2022). "Most of available studies are focused on G3BP1, which is frequently upregulated in a variety of cancers, where it seems to exert an oncogenic function." (PMID 34502337, 2021). "G3BP1 and PD-L1 were shown to be highly co-expressed in cancer tissues.G3BP2 knockdown or silencing by c108 also reduced PD-L1 expression due to enhanced mRNA degradation." (PMID 35004322, 2021). "Knocking-down G3BP1 reduces SG assembly in cancer cells treated with bortezomib (BZM), a proteasome inhibitor used for a range of hematological tumors, potentiating chemotherapeutic-induced cancer cell death." (PMID 34095105, 2021). "Transwell co-culture of WI-38 senescent cells depleted of G3BP1 significantly reduced cancer cell migration of A549 cells by ~15% when compared to control as demonstrated by wound healing assay after 24 h." (PMID 33020468, 2020). "Ultimately, two studies investigated the role of G3BP1 in cancer development in in vivo experiments." (PMID 32882814, 2020). "Overexpression of G3BP1 has been reported in multiple cancers including oral squamous cell carcinoma." (PMID 29728663, 2018). "To further evaluate the role of SG hyper-assembly in the translation defect caused by cancer-associated DDX3X mutations we took advantage of two RNA-binding proteins that are essential to SG assembly, G3BP1 and G3BP257." (PMID 27180681, 2016). "This hypothesis was also confirmed by the association of caprin-1 with G3BP1, c-Myc mRNA, and cyclins D1/D2 in polysomal fractions only in tylophorine- but not vehicle-treated carcinoma cells, whereas the c-Myc mRNA and cyclins D1/D2 mRNA levels were elevated in tylophorine-treated carcinoma cells." (PMID 25669982, 2015). "G3BP1 is therefore dispensable for TAT-RasGAP317–326 to mediate its genotoxin-sensitizing effect on cancer cells." (PMID 22205990, 2011). "By sensing cytosolic RNA, G3BP1/2 couple the cyclic GMP-AMP synthase (cGAS)-STING innate immune pathway to stress signaling in cancer and neurodegeneration, positioning these proteins as central hubs linking stress-responsive translation control to disease phenotypes." (PMID 41924133, 2026).
cancer (continued). "Moreover, G3BP1 is highly expressed in cancer cells and mediates cancer cell proliferation, metabolism, and invasion through a series of oncogenic pathways." (PMID 40762925, 2025). "Novel to this study, we identify ANO7 as a potential oncogenic driver in African men, through the formation of gene fusions with the cancer-related genes G3BP1 and PPFIA4, involved in androgen receptor (AR) and mitogen-activated protein kinase (MAPK) signalling, respectively." (PMID 37749167, 2024). "G3BP1 can bind to mRNA and guide selective translation and stress adaptation in cancer." (PMID 38164170, 2024). "In addition, G3BP1 has been reported to be highly expressed and play an important role in a variety of cancers." (PMID 36330442, 2022). "G3BP1 has been shown to function differently in different cancers." (PMID 35902727, 2022). "We submitted G3BP1 to Xiantao web for analysis of its expression in pan-cancer." (PMID 36330442, 2022). "G3BP1 is required for the activation of the senescence-associated secretory phenotype (SASP), and the effect of SASP on the proliferation and migration of cancer cells is very complicated." (PMID 34526993, 2021). "Many cytokines, such as HDGF, TGF-β, FGF2 and G3BP1, which are validated tumor promoters, participate in cell migration and metastasis induced by the m5C modification, indicating a strong correlation between the RNA m5C level and mobility of cancer cells." (PMID 34512153, 2021). "G3BP1 has been reported to be aberrantly expressed and have multiple effects on different cancers." (PMID 33726799, 2021). "In HCC, G3BP1 induction was shown to contribute to cancer cells migration by increasing SLUG expression, but whether this was associated with increased SG formation was not investigated." (PMID 34502337, 2021). "To address this hypothesis, we first examined SG formation in morusin-treated cancer cells by immunostaining for G3BP1, a representative marker for SGs." (PMID 32731602, 2020). "We further examined the impact of G3BP1-depleted senescent cells on cancer cell migration in vitro." (PMID 33020468, 2020). "However, the benefit of G3BP1 depletion or depletion of factors required for the alternative splicing of the SASP on cancer progression is evident." (PMID 33020468, 2020). "NSUN2 may affect these signaling pathways by regulating the binding of H19 RNA to G3BP1 and then affect the progression and malignancy of cancer cells." (PMID 32978516, 2020). "Notably, genetic inactivation of stress granule formation mediated by G3BP1 knockout sensitized cancer cells to morusin treatment." (PMID 32731602, 2020). "Importantly, we demonstrate that the SASP, in a G3BP1-dependent manner, are primary promoters of paracrine-mediated effects such as cancer growth." (PMID 33020468, 2020). "Indeed, it remains possible that the expression of G3BP1 displays a tissue-specific or cancer type-specific manner." (PMID 29717134, 2018). "The impact of miR-193a-mediated interruption of the caprin-1/G3BP-1/c-MYC/Cyclin D2 complex could be a potential target for anti-cancer therapeutic applications." (PMID 28211508, 2017). "Moreover, GAP161, a G3BP1-targeting peptide that inhibits G3BP1 and displays promising anti-cancer activity, was applied to MDA-MB-231 cells." (PMID 25962958, 2015).
cancer (continued). "Given that G3BP1 was previously reported as a Ras-GTPase-activating protein (RasGAP) SH3-domain-binding protein that enabled the Ras pathway, we explored whether G3BP1 KD influenced the Ras pathway in the OSCC cancer cells." (PMID 23341773, 2013). "However, fulvestrant can reverse the cancer-promoting effects of G3BP1 and mutant." (PMID 37904149, 2023). "By utilizing in vitro assays and in vivo animal models, we demonstrated that AEP-cleaved G3BP1 modulates tumor cell survival, and that inhibition of AEP sensitizes cancer cells to chemotherapeutic drugs." (PMID 40858563, 2025). "Intriguingly, our analysis identified proteins known as main stress granule markers (G3BP1, PABPC1, and TIA1) in ascitic fluids and secretomes of cancer cells after chemotherapy." (PMID 38898005, 2024). "G3BP1 deletion disrupts the cGAS pathway and blocks the expression of SASP factors, and these SASPless senescent cells disrupt senescence-mediated cancer cell growth in vitro and tumor growth in vivo." (PMID 36330442, 2022). "Based on function, the 12 FRGs can be grouped into four classes: Lipid metabolism (GPX4, LPCAT3, ACSL5, and ACSL6), antioxidant metabolism (CD44, SESN2, and AIFM2), iron metabolism (CISD1 and HSPB1), and cancer metabolism (SOCS1, FH, and G3BP1)." (PMID 34784264, 2022). "The 12 FRGs are divided into 4 categories according to their functions: lipid metabolism (GPX4, LPCAT3, ACSL5, ACSL6), antioxidant (CD44, SESN2, AIFM2), iron metabolism (CISD1, HSPB1), and cancer metabolism (SOCS1, FH, G3BP1)." (PMID 35559049, 2022). "Further, downregulation of G3BP1 repressed MMT process of MeT-5A cells and diminished cancer cell adhesion to MeT-5A cells." (PMID 33726799, 2021). "The results showed that G3BP1 and YWHAZ were co-localised in the cytoplasm of the examined cancer cells." (PMID 32989225, 2021). "Recent findings showed that RBPs, such as the Y-box binding protein (YBX1), which is overexpressed in many cancers including HCC, can upregulate G3BP1 expression by promoting its translation." (PMID 34502337, 2021). "Resveratrol, or epigallocatechin-gallate (EGCG) were, for example, reported to reduce G3BP1 expression in lung (H1299 and CL13) cancer cells, while attenuating NAFLD and restraining HCC development." (PMID 34502337, 2021). "To further explore the mechanism of the G3BP1-induced EMT, we focused on the Smad signaling pathway, which is known to play a major role in EMT-induced cancer progression and metastasis." (PMID 25962958, 2015). "If TAT-RasGAP317–326 modulates the ability of G3BP1 to cleave the c-myc mRNA it could affect the sensitivity of cells to apoptosis, in particular if c-Myc protein levels are increased because this can lead to cancer cell apoptosis, potentially via induction of Bim expression." (PMID 22205990, 2011). "In fact, G3BP1 has been reported to play oncogenic function independent of SGs formation in some malignant tumors." (PMID 38164170, 2024). "We used A549 cancer cells, transduced with lentiviral vectors carrying the mPlum cDNA and senescent WI-38 cells with or without G3BP1." (PMID 33020468, 2020). "However, we noticed that all SGs nucleators (TIA-1, TIAR, G3BP1, G3BP2, and CAPRIN-1) have an “enhancing” effect on cancer development properties, whereas USP10, a SGs inhibitor, has anti-cancer properties." (PMID 32882814, 2020). "Interestingly, G3BP1 and G3BP2 exhibit differential activity and functions in cancer." (PMID 40523886, 2025).
cancer (continued). "Furthermore, the search for CK2 substrates in the CIGB-300 interactome revealed that the peptide is able to interact with substrates playing central roles in cancer cell physiology, such as protein DEK, G3BP1, HDAC2, DNA topoisomerase 1 and 2-alpha, and others with oncogenic potential." (PMID 36672551, 2022). "Notably, G3BP1 KO cells display a higher level of PARP and caspase-3 cleavage upon morusin treatment compared to G3BP1 WT cells, suggesting that SG inhibition sensitizes the cancer cells to morusin." (PMID 32731602, 2020). "Therefore, further investigations are needed to identify specific compounds able to target G3BP1 in senescent cells and their implications on cancer progression, without the explicit removal or inhibition of senescence." (PMID 33020468, 2020). "However, G3BP1-depleted senescent cells did not affect cancer cell growth when compared to non-co-cultured A549 cells." (PMID 33020468, 2020). "Using immune-compromised NOD/SCID/IL2Rγ null (NSG) mice, we examined whether subcutaneous co-injection of cancer cells and senescent cells depleted or not of G3BP1 affected tumor growth and proliferation in vivo." (PMID 33020468, 2020). "Ultimately, the blockade of c-Myc mRNA transport by the tylophorine-mediated sequester of the caprin-1, G3BP1, c-Myc mRNA, and cyclin D2 mRNA-containing RNP complex may contribute significantly to the anti-cancer effects elicited by tylophorine in conjunction with the accumulation of c-Jun." (PMID 25669982, 2015). "However, we did not observe the polysomal colocalization of G3BP1, c-Myc mRNA, and cyclins D1/D2 mRNA with caprin-1 in the DMSO-treated carcinoma cells by sedimentation fractionation." (PMID 25669982, 2015).